MAP2K4 (mitogen-activated protein kinase kinase 4)
Diseases named in the same sentence as MAP2K4 in open-access papers (continued):
Sharing a sentence is not in itself a finding about the gene and the disease.
cancer (continued). "Interestingly, several of these small and large altered regions contain cancer-associated genes known to be involved in CRC and/or the metastatic process: i.e. the TPD52, FABP5, MAP2K4, LLGL1, FBLN1 and TYMP genes." (PMID 21060790, 2010). "After assessing the mRNA expression levels of selected genes, we assessed the expression of MAP2K4, MAP2K7, MAPK8, and MAPK9 proteins in cancer and normal colon tissue using images from the Human Protein Atlas." (PMID 41515982, 2025). "Both MAP2K4 and MAP2K1 are members of the MAPK gene family, and the MAPK pathway is known to be a crucial modulator of the cancer metastasis process." (PMID 38685065, 2024). "While MYCN is a well-recognized oncogene in several cancers including HCC46, MAP2K4 is reported to act as a tumor suppressor in HCC47." (PMID 35603298, 2022). "Meanwhile, the amplification peaks of cancer suppressors containing NF1 and MAP2K4 were detected in patients with high level of PPP2R2B expression." (PMID 33407498, 2021). "For six of these, the deletion peaks map to well-known tumor suppressor genes (CDKN2A, PTEN, RB1, MAP2K4, NF1, and SMAD4) that are frequently deleted in multiple cancer types." (PMID 31341961, 2019). "Among the 27 somatic mutations, 24 were restricted to the brain metastases, of which 4 affected cancer-related genes (i.e., FGFR2, MAP2K4, ATR and PIK3CA)." (PMID 29755676, 2018). "Other genomic regions with homozygous deletions also contained genes (MAP2K4 and miR-744 in 17p12 [Y15] and RPH3AL in 17p13.3 [Y12], respectively) that function as tumor suppressors or potential tumor suppressors in other cancers." (PMID 29190909, 2017). "Six of these genes (FHIT, TMSL3, PARK2, A2BP1, MACROD2 and MAP2K4) have been consistently reported as deleted in CRC and other cancers." (PMID 24367615, 2013). "Using DNA copy number data from 9,744 human cancer specimens, we demonstrate that linear deletion limitation exists and exposes deletion-limiting genes for seven known deletion targets (CDKN2A, RB1, PTEN, MAP2K4, NF1, SMAD4, and LINC00290)." (PMID 31341961, 2019). "MAP2K4, and MAPKAPK2 belong to the MAPK family, which is involved in cell proliferation, differentiation, and apoptosis, while CDC25B plays an important role in cell cycle, and is deregulated in several types of cancer." (PMID 27821810, 2016). "In addition, transcription factors, such as mitogen-activated protein kinase kinase-4 (MKK4), transforming growth factor beta (TGF-β), and the polycomb group (PcG) protein BMI1, were reported to suppress PTEN expression in several cancer models." (PMID 26284192, 2015). "Using DNA copy number copy number data from 9744 cancer specimens belonging to 39 cancer subtypes, we show that linear deletion limitation exists, and exploit it to expose deletion-limiting genes for seven deletion targets (CDKN2A, RB1, PTEN, MAP2K4, NF1, SMAD4, and LINC00290)." (PMID 31341961, 2019). "MiR-744-5p expression was reduced in the cancer cell lines independent of the host gene MAP2K4." (PMID 29899543, 2018).
tumor (100 papers, 2007 to 2026). "This appears counter-intuitive as MAP3K1 and MAP2K4 are encoded by genes having tumor suppressor-like properties." (PMID 29795445, 2018). "MAP2K4 was found to be a tumor and metastasis suppressor gene, which means that mutation and deletion of MAP2K4 will enhance the metastasis of tumors." (PMID 27148394, 2016). "This analysis also suggests opposing roles in tumor susceptibility for Map2k4 and Spry2, genes that exert opposite effects on mitogen-activated protein kinase (MAPK) signaling." (PMID 21244661, 2011). "Notably amplified regions included the KSR2, CANT1, MSI2 and MAP2K4 genes, all of which have been implicated in tumour progression, cell signalling, or regulation of proliferation." (PMID 40813389, 2025). "Consistent with our in vitro and in vivo findings, PDX models having mutations in MAP3K1 or MAP2K4 were significantly more sensitive to binimetinib than their wild type counterparts, with only the mutant tumors showing a decrease in tumor volume over time (p = 0.0023)." (PMID 29795445, 2018). "Due to the central and established role of MAP2K4 in tumor biology, we hypothesized miR-744 to be guilty by association, possibly augmenting or antagonizing MAP2K4s tumor-promoting effects." (PMID 30366472, 2018). "Of note, we observed that the association of MAP2K4 loss with underexpression is consistent with observations that it may play a role as a tumor suppressor." (PMID 17925008, 2007). "This is supported by the observed lower expression of MAP2K4 in tumor tissues compared to healthy tissues." (PMID 41515982, 2025). "Functionally downstream of MAP3K1 is MAP2K4, another dual-specificity kinase with tumor-suppressive properties via activation of JNK." (PMID 41465262, 2025). "MAP2K4 governs tumor development, apoptosis, the immune system, and inflammatory responses as a direct upstream activator of this pathway." (PMID 38510807, 2024). "The translocation that we identified in Patient 1 interrupted MAP2K4, a gene with far more supporting evidence that suggests it plays a role in catalyzing tumor development or metastasis." (PMID 34158539, 2021). "MAP2K4 is listed in COSMIC as potentially having a role in both tumor suppression and as an oncogene, depending on its expression level." (PMID 34158539, 2021). "Seven of the 64 tumour suppressors (ACVR2A, CSMD3, EPS15, MAP2K4, NF1, PBRM1 and RB1) had intronic mis-splicing mutations in multiple tissues." (PMID 33420369, 2021). "Of interest, we identified the top 10 differentially mutated genes between APOBEC-enriched and non-APOBEC-enriched samples, and among these, KRAS, CDHR5, JAK2, and MAP2K4 were previously shown to be closely related to tumor development." (PMID 32670354, 2020). "Several reports have revealed that MAP3K2 and MAP2K4 in some tumor types showed tumor-suppressive effects, particularly on tumor invasion." (PMID 32850377, 2020). "The role of MAP2K4 has been reported to be inconsistent functions in different types of tumors, which can serve as either a tumor suppressor or an oncogene." (PMID 31761784, 2019). "Our findings also suggest that MAP3K1 and MAP2K4 are potential drug targets in combination with MEK inhibitors, in spite of the fact that they are encoded by tumor suppressor genes." (PMID 29795445, 2018). "The most recent miRNA that was discovered to act as a tumour suppressor in OS is miR-363, which inhibits tumour progression and metastasis by targeting MAP2K4." (PMID 28272374, 2017). "Particularly, other groups have shown MAP2K4 knockdown decreases metastatic tumor growth in mouse models of breast and pancreatic cancer." (PMID 25019290, 2014).
tumor (continued). "As increased tumor size in-and-of-itself can affect metastatic spread, this demonstrates MAP2K4 has a primary effect upon the regulation of metastatic behavior." (PMID 25019290, 2014). "We also observed clear upregulation of the circRNAs and mRNAs of MAP2K4 in para-tumor tissues." (PMID 34857007, 2021). "Mutations with high VAFs indicated early appearance during tumorigenesis or tremendous contribution to later expansion of tumor cells, and the previous study demonstrated AKT1, CBFB, MAP2K4, ARID1A, FOXA1, and PIK3CA mutations have relatively high average VAFs in breast cancers." (PMID 33173047, 2020). "Indeed, loss-of-function mutations in the MAP2K4 gene (which encodes MKK4) exist in approximately 5% of tumors, and multiple lines of evidence indicate that the activity of MKK4 can suppress tumor progression." (PMID 32283767, 2020). "Similarly, MAP2K4- or ZDHHC17- positive tumor cells or proportions were raised overall in recurrent compared with matched primary tumors." (PMID 31938047, 2020). "Another tumor‐suppressing kinase is mitogen‐activated protein kinase kinase 4 (MKK4)." (PMID 30548122, 2019). "Its tumor suppressor role was demonstrated by targeting MAP2K4 and BCL2." (PMID 30945144, 2019). "Furthermore, proliferating cell nuclear antigen (PCNA) and Ki-67 expression as cellular markers for proliferation were ubiquitously higher in tumor tissues with MAP2K4 overexpression compared with those of the control tissues." (PMID 31761784, 2019). "MAP2K4 is located on chromosomal segment 17p11.2, which can be lost at a rate of approximately 7–10% in human epithelial cancers, particularly ovarian and breast cancers For this reason, it was initially presumed to be a tumor suppressor." (PMID 25019290, 2014). "However, novel tumor-specific eQTL are detected for several genes associated with tumor susceptibility, including IL18 (Il18), Granzyme E (Gzme), Sprouty homolog 2 (Spry2), and Mitogen-activated protein kinase kinase 4 (Map2k4)." (PMID 21244661, 2011). "Conversely, the MAP2K4 gene was down-regulated in 16/18 (89%) tumours." (PMID 21060790, 2010). "The remaining production of MAP2K4 may be due to non-tumor cells in the sample." (PMID 34158539, 2021). "To determine whether increased MAP2K4 expression increases metastatic potential, we examined the effect of MAP2K4 upon tumor growth and metastasis formation in vivo using an orthotopic murine model of human PCa metastasis specifically developed by us to quantify these parameters." (PMID 25019290, 2014). "Some CNAs overlapped between tumor types, others were tumor type-specific; losses of CDH20 and PTEN were observed in both tumor types, whereas amplifications seemed more tumor type-specific, such as EGFR and MAP2K4 in colon cancer and ERBB2 in breast cancer." (PMID 41537310, 2026). "Data from the Human Protein Atlas revealed differential protein expression of MAP2K4, MAP2K7, MAPK8, and MAPK9 between tumor and normal colon tissues; notably, MAPK8 protein expression did not correspond to the mRNA-level findings." (PMID 41515982, 2025). "Patients with low MAP2K4, MAP2K7 or MAPK8 expression or high MAPK9 or JUN in their tumours had greater metastatic frequency following tamoxifen treatment." (PMID 40826108, 2025).
tumor (continued). "While some of these truncations, such as NF1 in UCEC and MAP2K4 in BRCA, were often accompanied by lower-than-median mRNA expression in their respective tumor cohorts, their impacts were strikingly observed at diminished protein expression levels." (PMID 39775839, 2025). "In the remaining samples, homozygous deletions in three clinically important tumour suppressor genes, CDKN2A, MAP2K4, and PTEN occurred at analogous percentages in FF and FFPE samples." (PMID 39231944, 2024). "EBV encoding miR-BART22 enhances DDP chemoresistance by targeting MAP2K4 and activating MYH9/GSK3β/β-catenin-mediated tumor stemness pathways." (PMID 35105963, 2022). "MAP3K2 and MAP2K4, two members of the JNK axis, show a sequential function of upstream and downstream in tumor regulation." (PMID 32850377, 2020). "As expected, compared with the adjacent non-tumor tissues, both the MAP3K2 and MAP2K4 expression levels showed a prominent decrease in 20 HCC tissues, with significantly negative correlations to miR-519a-2-5p and miR-512-3p." (PMID 32850377, 2020). "The tumor suppressor genes, MAP3K2 and MAP2K4, were the direct targets, which were inhibited by the two miRNAs." (PMID 32850377, 2020). "MAP2K4 then phosphorylates and activates JNK, MAPK, and p38 MAPK, regulates inflammation and cell proliferation, and plays a vital role in tumor development." (PMID 31761784, 2019). "Two of the established tumour suppressors, CDH1 and MAP2K4, fall within known fragile sites FRA16B and FRA17A, respectively." (PMID 29089486, 2017). "Multiple tumor suppressor genes like PHF23, EIF5A, KCTD11, MAP2K4 and ALOX15B, have been reported to promote tumorigenesis when lost, indicating that gene expression regulation, signal transduction, arachidonate lipoxygenase and other cellular pathways are altered with the loss of chromosome 17p." (PMID 36750552, 2023). "Subsequent positional cloning revealed a homozygous deletion in MAP2K4, indicating MKK4 may be a novel tumor suppressor." (PMID 30548122, 2019). "However, there are additional reports indicating that MAP2K4 and JNK can participate in the promotion of tumorigenesis, suggesting that the molecular mechanisms of this signaling pathway in tumor progression is very complicated." (PMID 31761784, 2019). "As illustrated by the identification of CDH1/FRA16B and MAP2K4/FRA17B, two tumour suppressors located within known fragile sites, these properties are not always biologically separated, yet in both cases, our model was able to discern the signature of selection." (PMID 29089486, 2017). "Constitutive active MAP2K4, though not wild type, increases tumor size and circulating tumor cells in the blood and bone marrow." (PMID 25019290, 2014).
tumor (continued). "MAP2K4 overexpression increases the expression of heat shock protein 27 (HSP27) protein and protease production, with the largest effect upon matrix metalloproteinase 2 (MMP-2), both in vitro and in mouse tumor samples." (PMID 25019290, 2014). "Furthermore, bioinformatics analysis confirmed that MAP2K7 and MAPK8 appear to promote tumor aggressiveness and metastasis, whereas MAPK9 and MAP2K4 may have a protective or regulatory role in early stages of the disease." (PMID 41515982, 2025). "Gene expression changes between tumor with and without gene deletions were negative for MAP2K4 (fold change = −2.37, p = 0.0099), PTEN (fold change = −1.71, p = 0.10) and CDH1 (fold change = −1.59, p = 0.22), but close to one for RB1 (fold change = 1.08, p=0.62)." (PMID 26910888, 2016). "Therefore, wild type MAP2K4 does not increase tumor growth, but constitutive active MAP2K4 does." (PMID 25019290, 2014).
infection (53 papers, 2008 to 2026). The state of being infected such as from the introduction of a foreign agent such as serum, vaccine, antigenic substance or organism. "Quantitative real time PCR (qRT-PCR) of RNA in SCC-25 cells after 24 h of infection with P. gingivalis total membrane showed statistically significant up-regulation of the following genes: IκBκB (4.7 ×), MAP2K4 (4.6 ×), MAPK14 (4.2 ×) and IRF5 (9.8 ×) (p < 0.01) (n = 9)." (PMID 28056810, 2017). "Indeed, following infection with P. berghei or P. falciparum, the mosquito midgut epithelium undergoes profound cytoskeletal changes similar to those regulated by the Toll/MAP2K4/JNK signaling module in D. melanogaster." (PMID 22111877, 2011). "The genes IKBKB, IRAK3, IRF5, MAP2K4 (MEK4), MAPK14 (p38), MAPK8 (JNK1) and NFKB1 (p50) were upregulated not only in both cell types, but also after infection with whole bacteria of P. gingivalis W83 as well as with the membrane fraction." (PMID 28056810, 2017). "Interestingly, we found that depletion of MAP2K4/MKK4, widely considered a major regulator of JNK/MAPK signaling, decreased infection, indicating that JNK-mediated signaling may also impact SARS-CoV-2 replication." (PMID 37345956, 2023). "Nevertheless, the previously validated let-7e targets Tnfpaip3, Map2k4, Tbk1, and Tnf were upregulated during L. amazonensis infection, whereas the decrease in Chuk/IKBKA and Il10 expression during infection was not reversed by let-7e inhibition." (PMID 30555476, 2018). "Our microarray data revealed a major suppression of several components of the JNK pathway (MAP4K2, MAP3K5, MAP2K7 and MAP2K4), with the exception of JNK2 (also known as MAPK9), which was increased at 24 h; the other two Jun kinases, JNK1 and JNK3, were not significantly affected by infection." (PMID 28480889, 2017).
MAP2K4 also shares sentences with these, for which no sentence is quoted: bacterial infection (6 papers); cardiac hypertrophy (6); ischemia (6); fungal infection (5); Obesity (5); viral infections (5); adenoma (3); metastatic disease (3); steatosis (3); cervical cancer (2); colon adenoma (2); fibrosis (2); glaucoma (2); Hepatitis (2); Hyperglycemia (2); lung squamous cell carcinoma (2); melanoma (2); metastatic cancer (2); neuroblastoma (2); triple-negative breast carcinoma (2); acute myelogenous leukemia (1); Arthritis (1); Ataxia (1); atrial fibrillation (1); bladder cancer (1); bone tumor (1); brain tumor (1); Candidemia (1); candidiasis (1); cardiovascular diseases (1).
A further 49 diseases each share a sentence with MAP2K4 in 1 paper.